TNF (tumor necrosis factor)
Diseases named in the same sentence as TNF in open-access papers (continued):
Sharing a sentence is not in itself a finding about the gene and the disease.
colitis (continued). "In this study, we use the trinotrobenzene sulfonic acid (TNBS) colitis mouse model of CD to evaluate the colonic microbiota in healthy and colitic animals that produce Tnf or lack Tnf in order to determine how TNF suppression correlates with alterations in the microbiota and decreased inflammation." (PMID 25775453, 2015). "In addition to TNF secretion, release of eosinophil peroxidase promoted colitis identifying direct tissue-toxic mechanisms." (PMID 26200014, 2015). "RELM-β expression is also strongly induced in mouse models of spontaneous ileitis and during dextran-sodium sulfate driven colitis, where it appears to worsen intestinal inflammation by stimulating macrophage production of pro-inflammatory cytokines such as TNFα, IL-6, and RANTES." (PMID 26285214, 2015). "DSS-induced colitis enhanced the circulating levels of IL-6, TNF-α and GRO-α31." (PMID 26066467, 2015). "Thus, the gastrointestinal bacterial endotoxin LPS is able to increase plasma TNF-α and IL-1β levels by the activation of the low-grade inflammatory signaling pathways, leading to chronic inflammatory diseases such as colitis and rheumatism." (PMID 25689583, 2015). "Mice lacking nuclear factor kappa B essential modulator (NEMO) in intestinal epithelial cells (IECs) developed spontaneous colitis shortly after the birth due to excessive TNF-dependent apoptosis, followed by epithelial barrier breakdown and translocation of bacteria into the bowel wall." (PMID 26483605, 2015). "In this work, we showed that the induction of colitis by DSS administration caused a clear pro-inflammatory response (increase of COX-2, TNF-α, IL-12b, and IL-23 mRNAs) in the colon, which was significantly down-regulated after the administration of 5-ASA plus berberine." (PMID 26642326, 2015). "These dual directions of combination effect on PGE2 and TNF-α may partial explain why only marginal better effect on improvement of disease severity of colitis was induced by 5-ASA plus berberine." (PMID 26642326, 2015). "The inhibition of TNF signaling avoided the development of colitis." (PMID 26483605, 2015). "In this study, we mainly focused on the regulation of ID on proinflammatory cytokines but not Th2 cytokines, since it has been reported that the inhibitory effect of ID on DSS-induced colitis is due to the reduction of proinflammatory cytokines including TNF-α and IL-6 in previous study." (PMID 26104582, 2015). "Ac-food showed the highest expression of TNF-α and IL-6, which might be related to the severity of colon inflammation." (PMID 26140540, 2015). "Mild-to-moderate extensive colitis is initially treated with 5-ASAs, while severe or refractory extensive colitis is treated with oral or intravenous corticosteroids or anti-tumor necrosis (anti-TNF) agents." (PMID 24879406, 2014). "Furthermore, the redox-sensitive MAP kinases, ERK1/2 and p38 MAPK, were activated during TNFα-induced colitis." (PMID 25276054, 2014). "In addition, three days of oral Rb1 treatment potently inhibited the expression of TNF-α and IL-1β in the inflamed colon of mice with colitis." (PMID 24675731, 2014). "The observation that the expression of NOX1, NOXA1, NOXO1, and p22PHOX is increased during TNFα-induced colitis is in agreement with previous in vitro studies showing that treatment of T84 colon epithelial cells with TNFα increased NOX1 and NOXO1 expression at the mRNA and protein levels." (PMID 25276054, 2014). "In conclusion, MCL and DCIR modulate TNF-α production upon stimulation of APCs with heat-killed microbiota but play a limited role in intestinal immunity during the pathogenesis of DSS-induced colitis." (PMID 25068517, 2014). "Furthermore, TNFα production by these cells appears to be central to disease progression, as the severity of DSS-induced colitis is reduced in mice in which Ly6Chi monocytes are deficient in TNFα production." (PMID 24942685, 2014).
colitis (continued). "Even though experiments on mice with DNB-induced colitis showed that etanercept reduced levels of circulating TNF and prevented apoptosis of enterocytes equally well as infliximab, studies on humans proved that response rates to etanercept in CD treatment were comparable to placebo." (PMID 25045210, 2014). "Transgenic expression of IL-37 protects mice from lipopolysaccharide-induced shock and dextran sulfate sodium-induced colitis as well as concanavalin A-induced hepatitis, probably through inhibiting the production of pro-inflammatory cytokines IL-17 and tumor necrosis factor (TNF)-α." (PMID 27574641, 2014). "Interestingly, both IL-1β and TNF play a prominent role in extra-intestinal thrombosis in animal models of colitis." (PMID 24497828, 2014). "In addition, the redox-sensitive MAP kinases, ERK1/2 and p38MAPK, were activated during TNFα-induced colitis." (PMID 25276054, 2014). "Further pharmacological studies in animal models of colitis demonstrated that synthetic solomonsterol A effectively protects against development of clinical signs and symptoms of colitis and reduces the generation of TNFα, a signature cytokine for this disorder." (PMID 24473166, 2014). "There is evidence that TNFα is part of an early response in this colitis model." (PMID 25265225, 2014). "The neopterin, TNF-α, and interferon-γ levels of colitis group (group 2) were significantly higher than those of the group 1 (healthy control), group 3 (40 mg/kg: low dose strontium), group 4 (160 mg/kg: high dose strontium), and group 5 (prednisolone) (P < 0.05)." (PMID 25032214, 2014). "As TNFα-induced colitis was accompanied by a substantial increase in expression of the NOX1 subunits and an infiltration of neutrophils which could release large amount of ROS via NOX2, we next examined oxidative stress markers in the colon." (PMID 25276054, 2014). "In the mild colitis group, the expression of pro-inflammatory cytokines TNF-α, IL-6, IL-1β were increased to about 1.5 folds (p<0.05), and in the severe colitis group IL-6, TNF-α, IL-1β expression were increased to about 3, 2, and 1.5 folds compared to the water group." (PMID 24504372, 2014). "Indeed in the colitis model, treatment with the H4R antagonists completely inhibited the increase in tissue TNF levels." (PMID 23532396, 2013). "Studies in animal models of trinitro-benzene-sulfonic acid-induced colitis and concanavalin A (Con A)-induced hepatitis indicated that the blockade of IL-17A by IL-17R: FC is dependent primarily on the downregulation of IL-6 and TNF-α." (PMID 23977238, 2013). "During DSS-induced colitis NF-κB-regulated cytokines like IL-6 or TNFα are massively activated." (PMID 23977205, 2013). "Similarly, MPO activity in the dextran sodium sulfate (DSS)-induced colitis model was 22 times higher, and TNF-α level in plasma was approximately 100 times higher than that for the control group." (PMID 24001404, 2013). "IL-6 and TNF-α are key mediators in a number of experimental colitis models." (PMID 24223664, 2013). "Interestingly, it has been demonstrated that TNF downregulates KL through the transcription nuclear factor kappa B (NFkB) in animal models of chronic kidney disease and colitis." (PMID 23634661, 2013). "Colitis-induced upregulation of TNF-α, IL-1β, and IL-6 occurred predominantly in the SVF." (PMID 24386254, 2013). "Our results showed that both dosages (100 and 200 mg/kg) of sinomenine could suppress the expression of TNF-α to a remarkable degree in mice with TNBS-induced colitis." (PMID 24066068, 2013). "Interestingly, the TNF-α level was significantly higher in the colon of SIGNR3−/− mice during DSS colitis." (PMID 23882266, 2013).
colitis (continued). "Recent reports have shown that the neutralization of IL-17 using IL-17 receptor Ad:FC downregulates the expression of IL-6, tumor necrosis factor, etc., in colitis induced by trinitro-benzene-sulfonic acid, in atherosclerosis and in concanavalin A-induced hepatitis." (PMID 23977238, 2013). "The correlation between miR-155 expression and TNF-α level suggests that sinomenine-mediated effects on TNF-α may happen via miR-155 in TNBS-induced colitis." (PMID 24066068, 2013). "TNFα is highly expressed at early stages of colitis and may effectively reduce GC-C activation in the colon as the disease progresses." (PMID 24244444, 2013). "Based on these data, the presence of TNFα during the early stages of colitis may have the important effect of suppressing guanylin production and reducing GC-C signaling activity." (PMID 24244444, 2013). "Moreover, others have reported a reduction in colonic TNF-α by a cholinergic agonist anabaseine, in mice in which colitis was induced by DNBS." (PMID 23469045, 2013). "We recently reported that TNF-α and the G protein-coupled receptor (GPCR) agonist lysophosphatidic acid (LPA) lead to synergistic cyclo-oxygenase-2 (COX-2) expression, an enzyme strongly associated with the development of colitis-associated cancer." (PMID 23688423, 2013). "In this study, mice deficient in both TNF and IL-10 (T/I mice) were found to spontaneously develop severe colitis soon after weaning, without the need for exogenous triggers." (PMID 22848611, 2012). "Thus, our findings demonstrate that TNFα has an inhibitory effect on hepcidin expression in a second model of innate colitis." (PMID 22675442, 2012). "We wished to determine whether TNFα-mediated inhibitionof hepcidin expression was a unique feature of DSS colitis." (PMID 22675442, 2012). "The studies in TNBS or DSS-induced experimental colitis suggest that the exact role of TNF signaling via TNF-R1 or 2 may depend on model of colitis and mouse strains used and need to be interpreted carefully." (PMID 23285227, 2012). "Transgenic murine models of colitis with elevated epithelial TLR4 developed severe acute inflammation, greater colitis-associated neoplasia, and elevated levels of inflammatory and pro-oncogenic factors (TNFα, COX-2, PGE-2) versus wild type (WT) mice." (PMID 24696788, 2012). "Finally, the pro-inflammatory cytokines TNF-α, IFN-γ, IL-1β and IL-6, and anti-inflammatory cytokine IL-10 have been implicated in experimental and human colitis." (PMID 22844504, 2012). "The in vitro findings, together with the results for all S. cerevisiae strains analyzed in this study, suggest that Sc1-1 has beneficial biological activities reversing all aspects of colitis, including histological damage, diarrhoea and mucosal levels of the pro-inflammatory mediator TNF-α." (PMID 22848391, 2012). "We then tested the effect of the TNFα neutralizing antibody infliximab in mice with DSS colitis." (PMID 22675442, 2012). "The DSS colitis-induced decrease in Smad1 protein expression was prevented by TNFα neutralization." (PMID 22675442, 2012). "Other factors that may be involved in the inflammatory process in human IBD as well as in DSS colitis include pro-inflammatory cytokines such as interleukin (IL)-1β and TNF-α." (PMID 22562255, 2012). "Interestingly, TNF signaling via TNF-R1 or 2 also appears to have distinct effects on different models of experimental colitis." (PMID 23285227, 2012). "The first is that severe shigellosis (i.e. hemolytic uremic syndrome, thrombocytopenia and severe colitis >1 week) is associated with elevated IL-6 rather than TNF-α." (PMID 22887873, 2012). "Indeed, several biologic agents that block the actions of IL-1β and TNF-α have been successfully used in experimental colitis models." (PMID 23125487, 2012).
colitis (continued). "The pro-inflammatory cytokine TNF-α was the most prominent early biomarker of DSS-induced colitis based on its extensive up regulation during the onset of colitis induction and the fact that treatment of TNF-α neutralizing antibody significantly reduced DSS induced DAI." (PMID 21949848, 2011). "When used to treat colonic inflammation induced by TNBS administration to Balb/c mice, ciprofloxacin effectively protected against development of local signs of colitis and markedly reduced local generation of inflammatory mediators including IL-1β, IL-6, IFNγ and TNFα." (PMID 22046243, 2011). "Elevated levels of IL-4 were also seen in sash mice singly deficient in mast cells and in TNF-deficient mice that do not develop colitis under these conditions, compared with Il10−/− mice that develop severe colitis." (PMID 20808919, 2010). "Confirming the protective anti-inflammatory effect of n-3 PUFAs, transgenic fat-1 mice expressing a gene encoding an n-3 fatty acid desaturase which enables production of n-3 from n-6 PUFAs, exhibit low NFκB activity, reduced levels of TNFα and IL-1β, and are protected from colitis." (PMID 20122166, 2010). "Interestingly, inflammatory mediators in colonic cultures from colitic DKO mice were similar to those found in colon tissue during acute C. rodentium-induced colitis: TNF-α, IFN-γ, IL-1β, IL-17, and IL-6." (PMID 20976045, 2010). "Furthermore, the effect of VSL#3 on TNF-induced ileitis in heterozygous TNFΔARE mice and on colitis in IL-10−/− mice was investigated in the context of IP-10 expression in IEC." (PMID 19197385, 2009). "Therefore the increased local production of TNF-α and decreased colitis injury following WB intake are paradoxical." (PMID 19232107, 2009). "To evaluate the physiological impact of VSL#3 on experimental intestinal inflammation, we performed probiotic feeding studies with heterozygous TNFΔARE mice, an animal model for TNF-induced experimental ileitis, and IL-10−/− mice, an animal model for experimental colitis." (PMID 19197385, 2009). "The absence of colitis in B. vulgatus mpk mono-colonized IL-2−/−-mice was associated with an enhanced production of IL-6 and a decreased production of TNF-α in LP DC as compared to E. coli mpk mono-colonized mice." (PMID 18545662, 2008). "Thus additional mechanisms beyond simple shedding of receptor that has bound TNF likely account for the marked and sustained increase in stool TNF-RII during chronic DSS colitis in wild type mice." (PMID 18331642, 2008). "Thus, the potent down-regulation of peripheral and also mucosal TNF-α and IL-10 secretion by Gal-4 underscores the potential therapeutic use of Gal-4 and explains its beneficial effect in experimental colitis." (PMID 18612433, 2008). "Effects on colonic TNF and histologic severity of colitis were determined." (PMID 18331642, 2008). "B. vulgatus mpk mono-colonized mice only showed expression of IL-6 mRNA, whereas E. coli mpk mono-colonized mice, prone to develop colitis and SPF IL-2−/−-mice already suffering from colitis, revealed high levels of IL-1α, IL-1β, TNF-α, IFN-γ, IL-10 and IL-6 mRNA in the intestine." (PMID 18545662, 2008). "Longitudinal measurements of TNF in the stool of mice subjected to multiple cycles of DSS demonstrated that, although TNF levels are elevated in acute DSS colitis, these levels decrease spontaneously and eventually return to baseline despite ongoing severe inflammation." (PMID 18331642, 2008). "Finally, we have shown that Card15/Nod2 invalidation exacerbates the severity of TNBS induced colitis, as evidenced by the increase in all parameters characterising colonic inflammation (damages scores and mucosal levels of IL-1β, TNFα and IL-12)." (PMID 17565376, 2007). "Indeed, the proinflammatory effects of hIL-32β on collagen-induced arthritis mice and TNBS-induced colitis mice were, in part, canceled by a TNFα blockade." (PMID 17078892, 2006). "TNBS-induced colitis is a model of IBDs, in which TNFα plays an important role." (PMID 17078892, 2006).
colitis (continued). "Treatment with the selective TAAR1 antagonist EPPTB substantially improved colitis symptoms, including reduced weight loss, lower DAI scores, prevention of colon shortening, diminished tissue damage, and decreased expression of pro-inflammatory cytokines (TNF-α, IL-6, and IL-1β) in colonic tissue." (PMID 41550498, 2026). "Moreover, SN38-PLGA markedly alleviated colitis severity, as demonstrated by improved body weight, increased colon length, reduced disease activity and histological scores, and lower serum levels of TNF-α, IL-1β, and IL-6 compared with free SN38 or saline." (PMID 42099549, 2026). "In vivo studies using a DSS-induced colitis mouse model further demonstrated that HME-MUL-F2 could alleviate colitis symptoms, increase body weight and colon length, reduce pro-inflammatory cytokines (IL-1β, TNF-α, IL-6, MCP-1), and increase anti-inflammatory cytokines (IL-10)." (PMID 40283912, 2025). "Anti–IL-16 mAb treatment significantly reduced signs of disease in an animal colitis model (trinitrobenzenensulfonic acid (TNBS)-induced), such as weight loss, mucosal ulceration, myeloperoxidase activity (P < 0.001), as well as reduced mucosal levels of IL-1β and tumor necrosis factor-α (TNF-α)." (PMID 40529362, 2025). "Interestingly, amphiphilic cationic CDs as carriers delivered TNF-α siRNA to macrophages and mice that were induced with acute colitis; the results suggested that the CD-based delivery systems had some potential to deliver TNF-α siRNA for the treatment of inflammatory bowel diseases." (PMID 40143041, 2025). "Pathological changes of the colon mucosa confirmed the immunosuppressive effect of P5-MSCs, rather than P15-MSCs, in treating colitis, which was also supported by enzyme-linked immunosorbent assay (ELISA) analysis of the serum pro-inflammatory cytokine, tumor necrosis factor-alpha (TNF-α)." (PMID 39897564, 2025). "Other studies have evaluated the roles of immunosuppressive therapies in CMV reactivation and, as expected, corticosteroid-based therapy was linked with an increased risk of CMV-associated colitis, whereas anti-tumor necrosis factor (TNF)-alpha administration was not." (PMID 40284998, 2025). "Furthermore, HD-SD treatment significantly ameliorated the disease severity of acetic acid (AA)-induced colitis in rats, as evidenced by improved clinical signs, attenuated histological damage, and decreased levels of inflammatory factors (TNF-α, IL-6, and IL-1β)." (PMID 41008224, 2025). "In the DSS-induced colitis model in dogs, significant correlations were observed between specific microbiota and SCFAs (e.g., acetic acid, propionic acid, butyric acid, isovaleric acid, valeric acid, hexanoic acid), as well as pro-inflammatory markers (LPS, TNF-α, IL-1β)." (PMID 40395807, 2025). "Hence, to further dissect the protective effect of the combined treatment of vitamin C/allicin on DSS-induced colitis in mice, we quantified the relative gene expression levels of inflammation-related cytokines IL-1β, IL-6, and TNF-α in the middle and posterior segments of the colon." (PMID 40077487, 2025). "Moreover, combining anti‐TNF‐α therapy and therapeutic manipulation of crotonylation significantly alleviated colitis and intestinal barrier function, suggesting this might serve as a promising treatment approach to IBD." (PMID 40650658, 2025). "Suramin may reduce colitis severity by lowering TNF-α and NET levels." (PMID 40428786, 2025). "Quinic acid treatment could alleviate the symptoms of dextran sodium sulfate (DSS)-induced colitis in mice, maintain the intestinal barrier, down-regulate the expression of inflammatory factors such as IL-1β and TNF-α, and inhibit the activation of the MyD88/NF-κB signaling pathway." (PMID 40647020, 2025). "Moreover, RES alleviates colitis symptoms by enhancing the expression of tight junction proteins (TJPs), including Occludin and Claudin 1, while increasing anti-inflammatory cytokine IL-10 and reducing pro-inflammatory cytokines IL-1β, IL-6, and TNF-α." (PMID 39943187, 2025).